SRC (SRC proto-oncogene, non-receptor tyrosine kinase)
Diseases named in the same sentence as SRC in open-access papers (continued):
Sharing a sentence is not in itself a finding about the gene and the disease.
cancer (continued). "Here, we show that the oncogene src42A/SRC is a downstream target of Yki/YAP, and that SRC inhibitors are able to suppress YAP-induced tumor cell migration, providing SRC as an alternative target for Hippo-related cancer treatment." (PMID 34862372, 2021). "We describe CCT3833, a new drug that inhibits both RAF and SRC, which may be effective in KRAS-mutant cancers." (PMID 33130216, 2021). "•We synthesized new drug, CCT3833, that inhibits both RAF and SRC, and so may be effective in KRAS-mutant cancers." (PMID 33130216, 2021). "Problem 1 asked participants to predict molecules that bound the RETM955T-associated cancer pro-targets RET[M918T], BRAF, SRC, S6K, and did not bind the anti-targets MKNK1, TTK, ERK8, PDK1, and PAK3." (PMID 34520464, 2021). "Our study expands the role of PRL-3 in SRC signaling pathway modulation to include T-ALL, suggesting that PRL-3 might be a central regulator of the Src signaling network across multiple cancer types." (PMID 32001668, 2020). "We first explored the mRNA expression of MCL1, SRC, and Cofilin1 (CFL1) across cancers in the TCGA and Australian Pancreatic Genome Initiative (APGI) to identify contexts where a dual MCL-1, and SRC inhibitor strategy may be effective." (PMID 31735913, 2020). "Therefore, SRC, AKT, and PRDM are involved in regulation of cell differentiation and growth, and deregulation of these terms is the important processes in cancer." (PMID 34466507, 2019). "Both SRC and EIF4E play essential roles in multiple cancers, including NSCLC24,25." (PMID 31375661, 2019). "Cancer cells up-regulate the rate-limiting enzymes of glycolysis such as GLUT1, HK2, PKM2, and LDHA as a result of the expression of oncogenes including RAS, SRC, or EGFR." (PMID 29559564, 2018). "SRC is a non-receptor tyrosine kinase which has proven to be an important oncogene in various cancer types including breast, colorectal and EOC." (PMID 29435137, 2018). "Interestingly, several oncogenic signaling pathways, including ERK1/2, AKT, FAK and SRC, are regulated by expression of SKA1 in cancer cells." (PMID 29928475, 2018). "Therefore, the activation of critical signaling pathways related to tumorigenicity and cancer stemness, including JAK/STAT and SRC/FAK signaling pathway, were analyzed depending on TM4SF4 expression." (PMID 29254164, 2017). "However, they shared with carcinomas a similar prevalence of copy gains in several genes, including the chromosome 5p genes TERT, SDHA, and RICTOR, but also SRC and MYCL." (PMID 27873319, 2017). "Moreover, the ratio of pSRC/SRC was lower in CRC than in normal mucosa, indicating that the level of inactivating pY527 phosphorylation was reduced in the cancer compared with normal tissues." (PMID 27562229, 2016). "Collectively, our observations suggest that cellular transformation sensitizes certain types of cancer cells to the EV-mediated communication through mechanisms that may involve the activation of RAS and SRC pathways." (PMID 27437771, 2016). "FGFRs activate SRC in cancer cells and inhibition or silencing of SRC in cancer cells, but not in fibroblasts, prevents fibroblasts-mediated effects." (PMID 25973543, 2015). "SRC, LYN and CKB proteins or DNA methylation could serve as markers for predicting tumor progression and target in anti-cancer strategies." (PMID 26460485, 2015). "In particular, two non-receptor tyrosine kinases, FAK and SRC, which play central roles in regulating focal adhesion formation and turnover, are frequently dysregulated in cancer progression." (PMID 25860875, 2015). "SRC, also known as proto-oncogene c-Src, is a non-receptor tyrosine kinase that plays an important role in cancer progression by promoting survival, angiogenesis, proliferation, and invasion pathways." (PMID 25140799, 2014).
cancer (continued). "PTPD1, EGFR and c-SRC could then regulate actin and membrane dynamics needed to propagate EGF signals and consequently promote cancer progression." (PMID 25062045, 2014). "Taken together, our observations and analyses indicate that PPARβ/δ regulates SRC in human SCC, notably in skin SCC, and that this regulation also occurs in carcinomas of various tissue origins, thus revealing a broad pro-tumourigenic potential of PPARβ/δ via SRC upregulation." (PMID 24203162, 2014). "In addition to recruitment of adaptor proteins, activated RTKs present a binding and activating interface for several other cancer relevant signaling cascades including PLCG, SRC, and STAT." (PMID 23760067, 2013). "Interestingly, among several well‐established CRL5 substrates that were examined, including integrin β1, p‐SRC (Y416), ATM, RPB1, EGFR, DEPTOR, and NOXA, only integrin β1 consistently accumulated across all cancer cell lines upon APC11 knockdown using two independent siRNAs targeting APC11." (PMID 41159544, 2026). "SRC proto-oncogene, non-receptor tyrosine kinase (Src) is a node of convergence for receptor mediated signaling pathways, activating substrates in the MAPK, JAK/Stat3, and PI3K/AKT pathways to promote tumor cell survival, proliferation and invasion in various cancers, including GBMs." (PMID 39919036, 2025). "Similarly, modulating the activity of SRC and OPTN might affect autophagosome formation and selective degradation of mitochondria, influencing cancer cell survival and drug resistance." (PMID 39859167, 2025). "The sphere formation assay and ALDEFLUOR assay further confirmed that the cancer stemness markers, number and size of spheres, and ALDH activity were significantly reduced in troxerutin-treated cells, consolidating their targeting of the CD155/SRC/β-catenin axis to inhibit OS stemness." (PMID 40217455, 2025). "Notably, the METTL3-regulated SRC expression might be cancer type-specific and the relationship between METTL3 and c-Src in other types of cancer remains an open question." (PMID 40612868, 2025). "Notably, dual inhibition of both SRC and DDR2 leads to enhanced suppression of cancer growth." (PMID 39941857, 2025). "Since GAS6/AXL interaction has been described to trigger various signaling pathways in cancer cells, including PI3K-AKT, NFκB, RAS-MEK-ERK, SRC-FAK and JAK-STAT 8; it might be interesting to further elucidate the downstream mechanisms of action of sdAb20-Fc in AML." (PMID 38773967, 2024). "We then analyzed by RT–PCR the mRNA level of EGFR and of a small number of proteins involved in its activation and/or having prognostic value in cancer diseases: MMP-2 and -9; uPA; G Protein Coupled Receptor 1 (GPER1); Estrogen Related Receptor alpha (ERR-alpha); SRC; LDH-A and -B; HBEGF." (PMID 39329717, 2024). "Thus, these phosphorylation modifications of NPF and regulatory factors that can phosphorylate NPF, such as Shp1, Dyrk1A, Casein Kinase II, PAK4, SRC, ERK, Abl, Cdk5, etc., may provide targets for anti-invasive cancer therapy." (PMID 37026902, 2023). "Multiple studies indicate that targeting PTK6 and SRC may provide an advantage in cancer therapy although specificity of these inhibitors is lacking." (PMID 36228719, 2022). "TKS5 is crucial for the podosome formation and function in SRC-transformed mouse fibroblasts (SRC-3T3 cells), as well as for the formation of invadopodia in cancer cells, which contributes to the extracellular matrix (ECM) degradation by cancer cells and which promotes cell invasion and metastasis." (PMID 36430759, 2022). "Moreover, Eckert and colleagues showed that SRC, activated through TWIST1 transcription factor and platelet-derived Growth Factor Receptor (PDGFRα), mediates formation of invadopodia to degrade ECM and promote cancer cell invasion." (PMID 34193161, 2021).
cancer (continued). "Additionally, based on cancer cell line models, we show that MPM cells with a high Hippo-YAP activity are particularly sensitive to inhibitors of BCR-ABL/SRC, stratifying a unique MPM patient subset that may benefit from BCR-ABL/SRC therapies." (PMID 33805359, 2021). "Through the analysis of cancer cell line pharmacogenomics datasets, we showed that the INT-CDC signature was also predictive of higher sensitivity to tyrosine kinase inhibitors (TKIs), including EGFR, ABL, and IGFR signaling inhibitors, and to SRC and MAPK signaling inhibitors." (PMID 34200770, 2021). "For instance, Dasatinib (BMS-354825), a small molecular inhibitor of multiple tyrosine kinases with an IC50 of 0.55 nM toward SRC and the similar IC50 for other tyrosine kinases of the SRC family, has been shown to inhibit the progression of chronic myelogenous leukemia (CML) and other cancer types." (PMID 33842469, 2021). "In summary, depending on the tumor type, PTPN13 may regulate resistance to anti-cancer therapies through its anti-apoptotic role via the FAS pathway, or through regulation of secondary EGFR pathways (ephrinB1/ErbB and SRC/PKD1/AKT), or through an indirect action on microtubules mediated by ephrinB1." (PMID 33322542, 2020). "Since cLIF cells exhibited a higher activity of SRC and consequently an enhanced EMT and invadopodia formation, we therefore investigated whether treatment of cancer cells with AZD0530 alters LIF-regulated expressions of p-YAP1 and focal adhesion molecules, which might affect SRC activity." (PMID 30504771, 2018). "Therefore, VE-cadherin in cancer cells keeps its cytoskeleton binding capacity (actin-binding) but does not seem to require the interaction with β-catenin for SRC or FAK activation, as it does in endothelial cells." (PMID 27966446, 2017). "The particular combination of pERK1, SRC peak 6, and p70S6K peak 3 selected here to distinguish cancer tissue from normal tissue, may or may not indicate convergence of the included pathways in CRC signaling." (PMID 27562229, 2016). "Together, these data show that cancer therapeutics, such as IR or chemotherapy, to which tumor microenvironment cells are often exposed, induce GDNF secretion in these tumor microenvironment cells which then stimulates the stromal cells in an autocrine/paracrine loop via the SRC/ERK pathway." (PMID 25575823, 2015). "Therefore, SRC, LYN and CKB expression or DNA methylation could be useful markers for predicting tumor progression and targeting in anti-cancer strategies." (PMID 26460485, 2015). "Therefore by using approved non-small lung carcinoma drug Crizotinib, it may be possible to target SRC or FGR and therefore find its new uses in different cancer types." (PMID 25324859, 2014). "COX-2 also plays a role in cancer development through angiogenesis (increased expression of VEGF, promotion of vascular sprouting, migration and tube formation, induction of MMPs, and activation of EGFR); and through the activation of different oncogenes, including SRC, RAS, HER-2 and WNT." (PMID 24281071, 2010). "PROTACs in lipidation therapeutics can irreversibly knock down key cancer drivers that depend on membrane localization, such as RAS and SRC, rather than merely transiently inhibiting them." (PMID 40335986, 2025). "In cancer cells, the FAK and SRC are not properly regulated, which results from improper phosphorylation/dephosphorylation of tyrosine residues." (PMID 40563555, 2025). "In this regard, phosphorylation of paxillin at tyrosine residues 31 (Tyr-31) and 118 (Tyr-118) by the nonreceptor protein tyrosine kinase SRC and focal adhesion kinase 1 (FAK1) is essential for cytoskeleton assembly and cancer cell migration." (PMID 37607005, 2023). "Cancer tissues from three different patients exhibit higher expression of PTK6 and stronger activation of both PTK6 and SRC in comparison to the nonmalignant tissue." (PMID 36228719, 2022).
cancer (continued). "ESR2/SRC ratio was positively, very strongly correlated with PELP1/SRC ratio in tissue lack of any changes and strong in cancer affected tissue." (PMID 34207568, 2021). "The non-receptor tyrosine kinase SRC and other SRC family kinase (SFK) members are frequently hyperactivated in many cancer types, including MM." (PMID 32664483, 2020). "We found that SRC activates YAP and TAZ by repressing LATS but that SRC effector pathways known to regulate YAP and TAZ in other cell types are not playing a significant role in these cancer cells." (PMID 30559289, 2019). "The fact that SRC is required for YAP/TAZ activity in so many cell lines (25 of 28) suggests that this is an important and relevant regulatory pathway in these cancer types rather than a pathway unique to a few cell lines." (PMID 30559289, 2019). "In case of ESR2 Cr, cancer affected tissue showed a significant negative correlation with ESR1/ESR2 ratio (moderately strong) and positive with both ESR2/PELP1 (very strong) and ESR2/SRC (moderately strong)." (PMID 34207568, 2021). "GIT1 repressed SRC-mediated YAP/TAZ activity in each of the six cell lines we tested, suggesting that this regulatory mechanism is not unique to one cell line or cancer type." (PMID 30559289, 2019). "We therefore speculated that, similar to other pathway-targeted cancer drugs, cell lines in which the nintedanib-driven blockade of the FGFR/SRC/STAT3 axis fails to fully suppress STAT3 activity could activate the JAK/STAT3 axis as a compensatory mechanism, which might be responsive to silibinin." (PMID 34439322, 2021).
tumor (626 papers, 2001 to 2026). "Conversely, the downregulation of NFS1, GCLC, TP63, CD44, and SRC suggests a potential attenuation of antioxidant defense systems, thereby predisposing tumor cells to lipid peroxidation-mediated cell death." (PMID 40868287, 2025). "Immunohistochemical staining for Ki-67 demonstrated a reduced tumor proliferation rate following SRC deficiency after DOX treatment." (PMID 39664567, 2024). "The Src kinase, encoded by the SRC gene, is crucial to the TGFβ signaling pathway and promotes tumor cell invasion, metastasis, and immunosuppression, enabling tumors to evade immune surveillance." (PMID 39770551, 2024). "The Src kinase, encoded by the SRC gene, is an essential component of the TGFβ signaling pathway and influences tumor cell invasion and metastasis." (PMID 39770551, 2024). "The rest of the cells at the primary tumor site acquired several unique mutations (in genes SRC, SALL4, BAX, SMAD3), but with a slower mutation rate (PT2 PT3, PT5)." (PMID 38685065, 2024). "Aberrant SRC protein activation is associated with various tumors, and SRC activity is closely correlated with tumor progression." (PMID 39664567, 2024). "SRC is the first identified oncogene, and its aberrant activation has been implicated as a driving event in tumor initiation and progression." (PMID 36633714, 2023). "Mutated KRAS and other oncogenes such as EGFR and SRC can transfer to tumor cells through exosomes, promoting colon cancer invasion." (PMID 37305043, 2023). "Its phosphorylation by SRC was induced upon loss of cell adhesion and was thought to be linked to the metastatic potential of tumor cells." (PMID 36581908, 2022). "Our findings demonstrated that SRC is not only associated with tumor prognosis but can be used to predict the patient’s ability to respond to nCT." (PMID 36569844, 2022). "We found that the expression of UGT2B4 was positively associated with expression of multiple well-known oncogenes such as SPINK1, IDH1, MYC, and SRC and negatively associated with expression of well-known tumor suppressors such as CIC and ERF." (PMID 33391440, 2021). "Considering that SRC acts downstream the CSF-1 pathway and given that increased serum levels of this cytokine associate with higher aggressiveness of different tumor types, this study also analyzed the serum levels of CSF-1 in MM patients." (PMID 32664483, 2020). "Consistent with this, SRC gene copy number in stage IV CRC has been associated with left sided-tumours and liver metastases." (PMID 32717909, 2020). "Particularly integrin αVβ3 has been associated with tumor progression in various human malignancies and it co-operates with SRC oncogene to enhance anchorage-independent tumor growth and promotes lymph node metastases." (PMID 31231358, 2019). "How SRC induces tumour formation remains mysterious, in part because SRC is infrequently mutated in human CRC (2.9% as reported in cbioportal.org)." (PMID 31091767, 2019). "BRAF V600E and SRC mutations were mutually exclusive, and SRC mutation was significantly associated with left-sided tumor and liver metastasis compared to BRAF V600E mutation (P = 0.016 and P = 0.025, respectively)." (PMID 30792536, 2019). "It is noteworthy, however, that active SRC expression was strongly and significantly correlated with tumor recurrences and tumor-associated deaths specifically in the larynx (p < 0.001) but not the pharynx (p = 1.00)." (PMID 31731442, 2019). "This information was further and significantly extended in the present study, thereby uncovering a differential association of HERG1 expression with SRC expression depending on the HNSCC tumor site." (PMID 31731442, 2019). "In this analysis, we reported that 14 of 111 patients (13%) had SRC mutation, which was significantly associated with left-sided tumor and liver metastasis compared to BRAF V600E mutation." (PMID 30792536, 2019). "The role of SRC, as the proto-oncogene encoding a tyrosine kinase, has been studied in multiple tumours for many years." (PMID 29780284, 2018).